HYAL1 (hyaluronidase 1)
Diseases named in the same sentence as HYAL1 in open-access papers (continued):
Sharing a sentence is not in itself a finding about the gene and the disease.
cancer (continued). "Concerning the expression levels of the target genes evaluated in the present study, HYAL1, VEGFα, CD20, and PGR genes presented a similar pattern of response, showing significantly higher levels of expression both in benign and malignant tumours when compared to the control group." (PMID 38256245, 2024). "Due to the selective binding of HA to CD44, the micelle was efficiently captured by cancer cells and degraded by overexpressed hyaluronidase-1 (Hyal-1) intracellularly but was not degraded in normal cells." (PMID 33809633, 2021). "Some reports show that the expression of HYAL1 and HYAL2 depends highly on the cancer type." (PMID 32610620, 2020). "Inhibitors of Hyal-1 promise to pave the way for a deeper understanding of how the HA-hyaluronidase system is involved in the biology of cancer and non-cancer related disorders." (PMID 26343612, 2015). "In contrast, under-expression of HYAL-1 and HYAL-2 may contribute to poorer prognosis in pancreatic, ovarian, and endometrial malignancies, suggesting that the detrimental effects of hyaluronidases in cancer might vary depending on the type of cancer." (PMID 36613567, 2022). "HYAL1 mRNA was absent in all specimens, whereas HYAL2 was expressed as two splice variants, of which HYAL2-var2 was overexpressed in solid metastases compared to effusions and primary carcinomas (p < 0.001)." (PMID 23202930, 2012). "However, to our knowledge, this inverse relationship between Hyaluronidase-1 and hormone receptors has not been demonstrated in tissue samples from cancer patients." (PMID 21695196, 2011). "Indeed, the roles of HYAL1 and HYAL2 in cancer progression may vary depending on the cancer type." (PMID 33171800, 2020). "Thus analysis of HYAL1 and HYAL2 can have a great importance not only for better understanding of HA catabolism and human carcinogenesis but could provide therapeutic targets for cancer treatment." (PMID 18725949, 2008).
benign tumors (4 papers, 2009 to 2012). "A groupwise analysis indicated decreased HYAL1 in all non-benign tumors compared to normal ovaries (borderline: -58% (median), P = 0.05; grades 1+2: -79%, P = 0.05; grade 3: -69%, P = 0.01)." (PMID 19435493, 2009). "The malignant grade 1+2 and grade 3 tumors expressed also significantly less HYAL1 than benign tumors (P = 0.034 and P = 0.028, respectively)." (PMID 19435493, 2009). "We found that HYAL1 mRNA expression was elevated in clear cell and mucinous EOC tissue samples, but not in serous and endometrioid samples, normal ovaries or benign tumors." (PMID 21695196, 2011). "In the present work, we show that HYAL1 mRNA expression is elevated in clear cell and mucinous EOC tissue samples, but not in serous and endometrioid samples, normal ovaries or benign tumors." (PMID 21695196, 2011).
infection (3 papers, 2010 to 2024). The state of being infected such as from the introduction of a foreign agent such as serum, vaccine, antigenic substance or organism. "In contrast, the genes encoding hyaluronoglucosaminidases (HYAL1, HYAL2), the enzymes that degrade HA, were repressed, indicating that perhaps HA is not degraded during a B. pseudomallei infection." (PMID 21110886, 2010).
genetic disorders (2 papers, 2012 to 2024). "Of these, only deficiencies in HYAL1, HYAL2, HYAL3 and CEMIP have been identified as the cause or putative cause of human genetic disorders." (PMID 39056785, 2024).
HYAL1 also shares sentences with these, for which no sentence is quoted: prostate tumor (4 papers); bladder tumors (3); mucinous tumor (2); non-small cell lung carcinoma (2); Obesity (2); adenocarcinoma (1); adenoma (1); autoimmune thyroid disease (1); breast invasive carcinoma (1); cardiovascular diseases (1); cervical squamous cell carcinoma (1); chronic heart failure (1); chronic kidney disease (1); chronic obstructive pulmonary disease (1); clear cell carcinoma (1); cleft lip (1); COVID-19 (1); dengue (1); dysplasia (1); endocervical adenocarcinoma (1); endometrioid endometrial carcinoma (1); esophageal carcinoma (1); fibrosarcoma (1); gingivitis (1); glioblastoma multiforme (1); glomerular disease (1); graft versus host disease (1); hematological disease (1); keloid (1); laryngeal carcinoma (1).
A further 18 diseases each share a sentence with HYAL1 in 1 paper.